PPARG (peroxisome proliferator activated receptor gamma)
Diseases named in the same sentence as PPARG in open-access papers (continued):
Sharing a sentence is not in itself a finding about the gene and the disease.
thyroid cancer (continued). "Two earlier reports which examined PPARγ expression in different thyroid cancer cell lines need to be interpreted with caution as the cell lines used differed from those described here and in fact were shown later to be either redundant or not of thyroid origin." (PMID 22194735, 2011). "In this report, we show that PPARγ protein expression is associated with thyroid cancer type (ATC versus DTC) and not with response to agonist treatment." (PMID 22194735, 2011). "Clearly, a better understanding of the role of PPARγ in advanced thyroid cancer is needed." (PMID 22194735, 2011). "Finally, our studies of PPARγ depletion and overexpression show that this receptor increases thyroid cancer cell invasion." (PMID 22194735, 2011). "Furthermore, when we examined the levels of two cyclin-dependent kinase inhibitors, p21 and p27, which have been reported to be induced by PPARγ activation in other thyroid cancer cells, they were unchanged when PPARγ levels were manipulated." (PMID 22194735, 2011). "Thus these data were the first to convincinglylink the PPARγ gene to thyroid cancer.Altered PPARγ activity has subsequentlybeen shown to have a potential role in several types of thyroid cancer." (PMID 18989374, 2008). "A larger number of tissues were examined by immunohistochemistry in order to determine, and compare, the prevalence of PPARγ staining between normal, hyperplastic and neoplastic tissues, and to correlate staining with known prognostic variables of thyroid carcinomas." (PMID 15238980, 2004). "AsuragenmiR Inform (Austin, TX, USA) mutation analysis assay and Thyroid Cancer Mutation Panel by Quest Diagnostics (Madison, NJ, USA) are the two main commercially available mutational tests which test for known genetic alterations such as BRAF, RAS, RET/PTC, and PAX8/PPARγ." (PMID 24808946, 2014). "Chromosomal rearrangements involving genes known to be translocated in thyroid cancer were found in two samples, including one case with RET rearrangement involving the common RET partner CCDC6 and one case with the PAX8::PPARG fusion." (PMID 41123735, 2025). "In thyroid carcinoma, Pax8 exists as a gene fusion with peroxisome proliferator activated receptor gamma (Pax8/PPARG gene fusion), resulting in an oncogenic Pax8–PPARγ fusion protein." (PMID 34195082, 2021). "In the molecular diagnosis of thyroid cancer, the related molecular markers include TERT, BRAF, PAX8/ PPARγ, RAS and RET/PTC26." (PMID 31949496, 2020). "A small portion of thyroid carcinomas carries an oncogenic paired box 8 (PAX8) and PPARγ fusion protein." (PMID 31614690, 2019). "Thus PPARγ appears to be a marker for tumor aggressiveness and may play a role in the transition from differentiated (good prognosis) to undifferentiated (very poor prognosis) thyroid cancer." (PMID 22194735, 2011). "However, human ChIP-seq data would be difficult if not impossible to obtain due to the fact that antibodies to endogenous PPFP also bind to PAX8 or PPARG (our PPFP is epitope-tagged), as well as the fact that PPFP thyroid carcinomas are uncommon." (PMID 26595524, 2015). "Nuclear PPARγ expression was absent in differentiated thyroid cancer (DTC) cell lines and high in ATC cell lines." (PMID 24645981, 2014). "In thyroid cancer, the synthetic PPARγ agonist rosiglitazone was shown to enhance the uptake of radioiodine by thyroid tumors in a way apparently independent of PPARγ." (PMID 22654896, 2012). "Western blot analysis of the nine thyroid cancer cell lines showed that this antibody specifically recognizes PPARγ but also detects a nonspecific band migrating just below PPARγ in all cells." (PMID 22194735, 2011). "The undifferentiated thyroid cancer cells all had clearly detectable PPARγ, while the differentiated thyroid cancer cells lacked protein expression of this nuclear receptor even after increased exposure time of the blot." (PMID 22194735, 2011).
thyroid cancer (continued). "Finally, clinical trials using PPARγ agonists in advanced thyroid cancer have been disappointing and PPARγ levels were not assessed in most tumors." (PMID 22194735, 2011). "However, the rationale for administration of PPARγ ligands to treat thyroid cancer is not clear as some studies have shown a reduction in PPARγ expression, yet others revealed normal PPARγ expression or the occurrence of PAX8-PPARγ which can inactivate rather than decreasing PPARγ in thyroid cancer." (PMID 34557159, 2021). "This TXNIP expression pattern is opposite to what we previously reported with PPARγ, which is highly expressed in ATC cell lines and absent in DTC cell lines and whose forced expression confers a more aggressive phenotype in thyroid cancer cells in vitro and in vivo." (PMID 24645981, 2014). "Cyclin D1 isknown to be overexpressed in human thyroid carcinomas and in vitro addition of aPPARγ agonist to human ATC cell linessuppresses cyclin D1 levels, confirming thatthis effect is related to alterations in PPARγ rather than TRβ." (PMID 18989374, 2008). "Thyroid cancer cells thatdid not express PPARγ showed no growth inhibition after treatmentwith troglitazone and 15d-PGJ2 compared with thyroid cancer cellsthat did express PPARγ and were sensitive to growth inhibition bytroglitazone and 15d-PGJ2, suggesting PPARγ-dependent growth inhibition." (PMID 18615184, 2008).
Stroke (85 papers, 2008 to 2026). Sudden impairment of blood flow to a part of the brain due to occlusion or rupture of an artery to the brain. "The PPARγ agonist Pioglitazone was recently associated with lower risk of recurrent stroke in patients with IR, prediabetes and T2D with a history of stroke or transient ischemic attack." (PMID 36835405, 2023). "Hypoglycemic agents such as pioglitazone reduce the risk of stroke recurrence by activating PPARγ signaling in adipocytes, immune and endothelial cells, and other tissues." (PMID 36248006, 2022). "Second, we tested effects of rFGF21 on PPARγ activation-associated BBB protection after focal stroke in T2DM mice." (PMID 32012810, 2020). "Rg1 was reported to suppress inflammation and preserve the brain tissue from stroke insults, and the underlying mechanism was related to the activation of PPARγ/HO-1 and PPARγ-regulated pathways." (PMID 31068769, 2019). "The current findings should aid future researchers in better characterizing IRF6 as a novel therapeutic target for modulating PPARγ -associated signaling cascades for purposes of stroke treatment." (PMID 28526834, 2017). "PPARγ plays a critical role in regulating gene expression linked to mitochondrial biogenesis and inflammatory responses, both of which are key to reducing neuronal damage post-stroke." (PMID 39519132, 2024). "We hypothesize that targeting PPARγ with amorfrutin B causes a neuroprotective effect when administered post-treatment in experimental models of stroke and perinatal asphyxia in vitro." (PMID 34440058, 2021). "Next, we selected PPARγ as our major target to investigate the therapeutic mechanisms underlying rFGF21 treatment in T2DM stroke, since PPARγ has been well-known for its pivotal role in anti-inflammation, antioxidative stress, and subsequent vascular protection." (PMID 32012810, 2020). "In this study, the present study aims at exploring the therapeutic effects of MA by observing the inflammatory cytokines and M1/M2 polarization markers in the cortex of the mouse experimental stroke model and also unravel the potential mechanism with PPARγ activation and the underlying mechanism." (PMID 25889216, 2015). "For example, the synthetic PPARγ-activating compounds termed thiazolidinediones (e.g., pioglitazone, rosiglitazone) show evidence of ameliorating cerebral damage and neurological outcomes in animal models of cerebral ischemia as well as lowering recurrent stroke risk in stroke patients." (PMID 28526834, 2017). "FGF21 upregulates the PPARγ pathway to alleviate inflammation in microglia and macrophages and protect brain microvascular endothelial cells, playing a positive role in stroke." (PMID 38733164, 2024). "Amorfrutin B is a selective PPARγ modulator that we demonstrated to be a promising neuroprotective compound in cellular models of stroke and perinatal asphyxia." (PMID 38949694, 2024). "As a multipotent regulator of antioxidant regulation, anti-inflammatory and microglia polarization, PPARγ has become a potential therapeutic target for stroke." (PMID 38597270, 2024). "It was also shown that activation of the peroxisome proliferator-activated receptor gamma (PPARγ) pathway, in conditions of ischemia/stroke, regulates the balance of pro-/anti-inflammatory microglia polarization." (PMID 37047292, 2023). "Although the neuroprotective potential of PPARγ agonists for the treatment of brain hypoxia and stroke is well-accepted, only certain agonists, namely thiazolidinediones, appeared effective when applied as a post-treatment." (PMID 36324052, 2023). "Given the established secondary preventive effect of pioglitazone, lobeglitazone, another thiazolidinedione-based PPARγ agonist, likely plays a protective role in stroke patients with T2D." (PMID 37147722, 2023). "In a word, Sirt1 mediated the synthesis of triglyceride and inhibition of neuronal apoptosis after stroke, which was associated with the QKI 6 and the PPARγ/PGC-1α signaling pathway." (PMID 37622049, 2023).
Stroke (continued). "The neuroprotective effect of amorfrutin B involves PPARγ activation and epigenetic modifications, which position this compound among the most promising anti-stroke therapeutics." (PMID 36324052, 2023). "DAI has neuroprotective effects in stroke conditions and has shown peroxisome proliferator-activated receptor gamma (PPAR-γ)-dependent therapeutic effects in brain cells and has huge potential to improve synaptic functioning in cultured neurons." (PMID 36838751, 2023). "Among them, the crosstalk between Notch and NF-κB signaling pathway can inhibit the expression of PPARγ, which will decrease the expression of PPARγ after stroke, thereby aggravating the inflammatory response." (PMID 36818470, 2022). "Rosiglitazone, a PPARγ agonist, significantly improves the pathological changes in the brain’s white matter after stroke while protecting the white and gray matter of the brain and promoting long-term functional recovery after stroke." (PMID 36296682, 2022). "In stroke and ischemia models, increased expressions of CD36 were demonstrated mainly by microglial cells in a PPARγ-dependent manner, which was associated with the resolution of neuroinflammation through phagocytosis." (PMID 36310859, 2022). "Multiple studies have shown that PPARγ is a key participant in promoting polarization of microglia to the M2 phenotype in various experimental stroke models." (PMID 35720361, 2022). "Our results showed there were significant reductions of both PPARγ downstream genes after stroke (there was 96.8% reduction in CD36 mRNA level and 73% reduction in FABP4 mRNA level) in db/db mice compared to those in db/+ mice." (PMID 32012810, 2020). "We found a severe decline in PPARγ activity after stroke in db/db mouse brain compared to in db/+ mice, but it was almost completely rescued by the delayed rFGF21 administration." (PMID 32012810, 2020). "Vehicle or IL-4 treatment in PPARγ-OPC KO mice resulted in similar neuronal tissue loss and white matter lesion 35 d after stroke." (PMID 31226122, 2019). "Recently, PPARγ has been shown to exert neuroprotection in stroke both in rodent models and humans, which makes PPARγ activators a potentially ideal treatment for ischemic brain injury." (PMID 30622558, 2018). "Nevertheless, programming neutrophils to the anti-inflammatory N2 subtype by a Peroxisome proliferator-activated receptor gamma PPARγ agonist has been used to obtain a beneficial outcome in stroke." (PMID 29383445, 2018). "Further investigation into IRF6 and other PPARγ co-regulators should provide additional insights into PPARγ’s cytoprotective role in the cerebrovascular endothelium following stroke." (PMID 28526834, 2017). "PPARγ plays an important role in stroke, cardiovascular, age-related macular degeneration, and other inflammation-related diseases." (PMID 29163813, 2017). "Activation of peroxisome proliferator-activated receptor gamma (PPARγ) in the cerebrovascular endothelium is a key suppressor of post-stroke brain damage." (PMID 28526834, 2017). "MA has anti-inflammatory effects in MCAO mice in a PPARγ-dependent manner, making it a potential candidate for stroke treatment." (PMID 25889216, 2015). "PPARγ expression was dramatically increased in ischemic neurons and the treatment with T0070907, a PPARγ antagonist, reversed rosiglitazone-mediated protection after stroke." (PMID 25246934, 2014). "PPARγ agonists promote neuroprotection in models of stroke, AD, HD, PD, MS, and spinal cord injury, via anti-inflammatory or antioxidant-dependent mechanisms." (PMID 25628533, 2014).
Stroke (continued). "PPARγ agonists seem to protect neurons not only following acute CNS injury including stroke, spinal cord injury and TBI after which massive inflammation plays a detrimental role, but also in neurodegenerative conditions including multiple sclerosis, AD and PD." (PMID 25628533, 2014). "Complementary studies examined PPARγ expression, DNA binding, and PPARγ transcriptional activity after stroke induced in rats." (PMID 25246934, 2014). "In vivo, activating PPARγ in a middle cerebral artery occlusion model of stroke reduces infarct size and lowers cyclin D1, a protein involved in programmed cell death." (PMID 24215544, 2013). "Interestingly, in a mouse stroke model, clearance of dead cells by macrophages was regulated by PPARγ and STAT6, which also triggered the regeneration of the area around the infarction." (PMID 40867169, 2025). "Further research on IRF6 and other co-regulators of PPARγ could offer a deeper understanding of PPARγ’s protective effects in the cerebrovascular endothelium following a stroke." (PMID 40149423, 2025). "Various 5-HTRs can increase serotonin levels and affect other signaling pathways, such as peroxisome proliferator-activated receptor gamma (PPARγ), which has been correlated with multiple brain-related diseases and conditions, such as stroke, cancer, and tranumatic brain injury." (PMID 38741139, 2024). "Preclinical research using PPARγ agonists has shown that these drugs also reduce stroke-induced brain damage in animal models of stroke, effects that could be behind the improved stroke recovery." (PMID 36835405, 2023). "However, the neuroprotective capacity of selective PPARγ modulators in cellular and animal models of stroke is much less recognized than that of PPARγ agonists." (PMID 34440058, 2021). "Activation of the PPARγ-Nrf2-NF-κB signalling pathway can reduce neuroinflammation after stroke." (PMID 34434246, 2021). "R1 includes genes and their products involved in circadian rhythms, while its major hub NCOR1 in macrophages blocks the pro-atherogenic functions of peroxisome proliferator-activated receptor gamma (PPARγ) (Oppiet al., 2020), greatly implicating stroke pathophysiology." (PMID 33224479, 2020). "In addition, activation of RXRs or/and PPARγ by receptor agonists has been associated with neuroprotection from several diseases such as AD, PD, ALS, MS, and stroke." (PMID 30402708, 2019). "Finally, OPC-specific PPARγ KO (PPARγ-OPC KO) mice were used to confirm the importance of PPARγ signaling in IL-4-enhanced oligodendrogenesis in an in vivo stroke model." (PMID 31226122, 2019). "Based on findings in other and our studies, we hypothesized that the activation of PPARγ elicited by the administration of PGZ after stroke may be beneficial due to not only its anti-inflammatory effects but also its promotion of neurogenesis." (PMID 29110250, 2018). "We demonstrated that PGZ prevented ischemic brain damage in OVX rats when it was administered before stroke and that this was associated with the upregulation of anti-apoptotic and survival genes via the trans-activation of STAT3 and PPARγ in the peri-infarct region." (PMID 29110250, 2018). "We are continuing to assess the potential role of PGZ in the activation of post-stroke PPARγ because such findings may lead to treatments that improve the outcomes in stroke patients." (PMID 29110250, 2018). "On this basis, PPARγ shows promise as a potential pharmacotherapeutic target for stroke patients." (PMID 28526834, 2017). "PPARγ agonists (derivatives of thiazolidinediones, e.g., troglitazone, rosiglitazone and pioglitazone) have been associated with neuroprotection in different neurological pathologies, including AD and PD, cerebral ischemia, MDD and stroke." (PMID 29137141, 2017). "All these data suggest that intrinsic PPARγ may be important in limiting stroke mediated injury and that further activation by TZDs may improve outcome." (PMID 27352979, 2016).